CRP (C-reactive protein)
Diseases named in the same sentence as CRP in open-access papers (continued):
Sharing a sentence is not in itself a finding about the gene and the disease.
depression (continued). "However, there was significant heterogeneity of effect size between studies that may be attributable to clinical heterogeneity, with higher CRP in severe depression (Cohen's d = 0.50) than in mild/moderate depression (Cohen's d = 0.37), as well as methodological differences between studies." (PMID 29764522, 2019). "Therefore, if CRP and IL-6 cannot be simply considered biomarkers of inflammation, then the association of CRP and IL-6 with the development of depressive symptoms cannot be interpreted to provide evidence for a link between inflammation and depression that is not due to a medical condition." (PMID 30769887, 2019). "For example, inflammatory proteins, such as C-reactive protein (CRP), and cytokines, such as interleukin (IL)-6 and tumor necrosis factor (TNF)-α, have been elevated in people with depression." (PMID 30987242, 2019). "Thus, increases in plasma IL-6 and to a lesser extent CRP have been found in elderly individuals taking care of a spouse with a chronic medical condition, persons with a low socioeconomic, victims of childhood abuse or maltreatment and patients with depression in comparison to respective controls." (PMID 30769887, 2019). "We also observed that CRP and IL-6 correlated with lower score on HADS depression items in the control group (p = 0.009, β = −0.655 and p = 0.003, β = −0.630)." (PMID 30185816, 2018). "Peripheral inflammatory response can lead to depression, the inflammatory factors (IL-6, TNF-α and CRP) are mainly synthesized by monocytes and produce inflammatory response and promote immune response." (PMID 30181997, 2018). "The control group scored more than 5% lower on the CATest, Zung Anxiety, Zung Depression, COMPASS 31, hs-CRP (all indications of better health); and had higher scores on the MAIA (especially body listening) and higher blood levels of testosterone and DHEAS." (PMID 30406067, 2018). "Further, the CSF levels of CRP seem to be increased in PD patients with dementia (PDD), and correlate with depression and fatigue in patients with PD22." (PMID 30185816, 2018). "Patients’ depression was assessed using Beck depression inventory second edition (BDI-II) biochemical parameters (hemoglobin, serum albumin, etc) and CRP levels were measured at baseline and at weeks 4, 8 and 12 of the study." (PMID 28487875, 2017). "The increasement of the pro-inflammatory cytokines such as CRP and IL-6 were found in patients with WMH, depression, stroke and PSD." (PMID 29051732, 2017). "Finally, we do not have repeated measures of inflammatory cytokines (IL-6, ACT and CRP) and therefore could not analyse whether long-term exposure to high levels of inflammatory markers are associated with depression." (PMID 25877654, 2016). "Coupled with increases in acute phase proteins, such as complement protein, C-reactive protein (CRP), and haptoglobin, elevated pro-inflammatory cytokines have been observed in major depression." (PMID 27429749, 2016). "Another analyte, high sensitivity C-reactive protein (hs-CRP), was found to be a highly specific baseline biomarker when evaluating patient response to Infliximab in treatment-resistant depression (TRD)." (PMID 27199779, 2016). "Among 3024 subjects between 70 and 79 years of age, those who scored higher on a standardized depression scale also had significantly higher levels of IL-6, TNF, and CRP." (PMID 28030615, 2016). "Five older participants with major depression and 13 controls underwent PET and multimodal 3T magnetic resonance imaging (MRI), with blood taken to measure C-reactive protein (CRP)." (PMID 27758838, 2016). "Meta-analysis studies have reported higher levels of inflammatory cytokines (such as interleukin-6, (IL-6)) and acute phase proteins (such as C-reactive protein (CRP)) in the peripheral blood and cerebrospinal fluid of patients with major depression." (PMID 25877654, 2016).
depression (continued). "Finally, other proposed mechanisms by which insomnia might increase the risk of depression included increasing levels of inflammatory markers, such as C-reactive protein and interleukin-6 (IL-6), which indicated low-level systemic inflammation was a predictor of depression development." (PMID 27816065, 2016). "Elevations in proinflammatory cytokines like prostaglandin E2 (PGE2), C-reactive protein (CRP), TNF-α, IL-1β, IL-2, and IL-6 have been reported in major depressive disorder and, at times, have shown a dose-response with severity of depression." (PMID 26550011, 2015). "CRP, TNF-α, and e-Sel were found to have significant moderating effects on the development of storage LUTS (1.06, 0.91–1.96, R2 change: 12.7%), depression (1.17, 1.01–1.54, R2 change: 9.8%), and anxiety (1.35, 1.03–1.76, R2 change: 10.6%), respectively." (PMID 26445118, 2015). "Determine the serum levels of inflammatory markers (CRP, IL-6 and TNF-α) in elderly diabetic patients with depressive syndrome alone or with coexisting MCI." (PMID 25793613, 2015). "The aim of the study was to determine the serum levels of CRP, IL-6 and TNF-α in elderly diabetic patients with depressive syndrome alone or with coexisting mild cognitive impairment (MCI)." (PMID 25793613, 2015). "We used a sample of 145 elective CABG patients and measured depression symptoms using the Beck Depression Inventory (BDI) prior to surgery and collected baseline measures of CRP." (PMID 24239712, 2014). "To this end, we measured C-reactive protein (CRP), TNF-α, IL-6 and soluble interleukin-2 receptor (sIL-2R) in the blood of MSA patients and healthy controls, all assessed for symptoms of depression, anxiety, fatigue and sleep difficulties." (PMID 23626805, 2013). "Levels of Interleukin-6 (IL-6) and C-creative protein (CRP) indicating systemic inflammation are known to be elevated in chronic diseases including chronic obstructive pulmonary disease (COPD) and depression." (PMID 23676005, 2013). "Increased C-reactive protein (CRP) levels in depressed men predict not only severity of the current depressive episode, but also recurrent depression." (PMID 22747645, 2012). "Severity of depression was measured by HRSD scale and anti-inflammatory activity was measured by reduction CRP, ESR and WBC count." (PMID 21701640, 2011). "Cross-sectional surveys and case-control studies have also found elevated blood markers of inflammation, including CRP and IL-6, in patients with MDD relative to healthy controls, and that these markers were positively correlated with depression symptom severity." (PMID 19936106, 2009). "Meta-analyses and systematic reviews corroborate these findings, showing increased levels of interleukin-6 (IL-6), interleukin-8 (IL-8), tumor necrosis factor-alpha (TNF-α), and C-reactive protein (CRP) across major psychiatric disorders, including depression, anxiety, schizophrenia, and BD." (PMID 41598300, 2026). "Persistent low-grade inflammation, as reflected by stable CRP levels, has been reported in previous studies and is thought to contribute to long-term comorbidities in people living with HIV, including neurocognitive decline and depression." (PMID 41575658, 2026). "The study relied on specific inflammatory markers (CRP, NLR, and PLR) and self‐reported measures of depression, which may introduce biases." (PMID 40851223, 2026). "Depression, alcohol use, and AUD were unrelated to CRP and the pro-inflammatory index." (PMID 41969823, 2026). "Feature selection identified 13 predictive variables: age, operation time, length of hospital stay, pain score, white blood cell count, albumin, C-reactive protein, CA125, education level, history of depression/anxiety, postoperative insomnia, fatigue, and opioid analgesic use." (PMID 42023444, 2026). "In addition, compared to C-reactive protein (CRP), AGP had a stronger predictive effect on depression using the ROC curve." (PMID 40530060, 2025).
depression (continued). "NMDARs are expressed on immune cells that may release GLU endogenously and C-reactive protein (CRP), various cytokines and TNF-α are increased in patients with depression." (PMID 40520195, 2025). "In several meta-analyses, it has been established that proinflammatory cytokines and acute phase proteins are elevated in patients with depression, and levels of IL-6, TNF, and C-reactive protein (CRP) have been shown to be higher in the blood of depressed patients compared to healthy controls." (PMID 40795291, 2025). "The serum levels of Hs-CRP and IL-6 after delivery in women with depression were significantly higher than in women without depression." (PMID 40682534, 2025). "Young adults who have experienced childhood trauma exhibit heightened inflammation, evident through increased levels of CRP and the count of white blood cells, regardless of their depression diagnosis." (PMID 41301474, 2025). "Several meta-analyses have revealed increased levels of inflammatory cytokines, such as IL-1β, soluble IL-2, IL-6, TNF-α, C-reactive protein (CRP), and inflammatory mediator PGE2, in the peripheral blood and cerebrospinal fluid (CSF) of patients with the major depressive disorder." (PMID 39936956, 2025). "In case of C-reactive protein (CRP), majority of studies focus on serum concentration and its potential impact on pathophysiology of depression, with scarce studies focused on potential SNPs impact on serum levels and not antidepressant response or remission vs. resistance." (PMID 41303496, 2025). "Research suggests that fats and saturated fatty acids may contribute to inflammation by elevating levels of inflammatory cytokines and C-reactive protein (CRP), potentially exacerbating PMS symptoms, including depression." (PMID 40640956, 2025). "In patients with CRP < 1 mg/L, responders (again, vs. current MDD) show inhibition of interferon signalling, confirming and expanding upon previous RNA-seq findings identifying upregulation of genes in this pathway in people with MDD or treatment-resistant depression in comparison with controls." (PMID 39271754, 2025). "Comparison DM, DR, POAG, AD, APOE E4 status and level of CRP in patients with and without depression and/or DM and the gender differences." (PMID 40778276, 2025). "Exposure to trauma was measured from 5 to 11 years of age; C-reactive protein and interleukin-6 levels were measured at 9 years; and depression, anxiety disorders, negative symptoms and psychotic experiences were assessed at 24 years." (PMID 40814293, 2025). "A notable observation in the current study is that elevated CRP was associated with pain-type somatic symptoms, independent of mental health status, indicating that there may be inflammatory processes underlying pain-type somatic symptoms, independent of anxiety or depression symptom." (PMID 40823322, 2025). "Again, it was found that CRP predicted worsening depression in women, but not in men, while depressive symptoms predicted increasing inflammation for men, but not for women." (PMID 40305313, 2025). "LASSO regression identified six variables with non-zero coefficients as significant predictors of depression: completion of 9 years of compulsory education, sleep disorders, anxiety, CRP levels, ALSFRS-R total scores, and SIRI values." (PMID 41018179, 2025). "Similarly, human studies have consistently found that circulating levels of at least 15 markers such as CRP, IL-2, IL-6, CCL3, TNF-α, and TNF-β (also known as Lymphotoxin-alpha) were increased in patients with depression." (PMID 41010394, 2025). "Neither acetate (P = 0.43), propionate (P = 0.24), nor C-reactive protein (CRP) (P = 0.83) significantly predicted depression outcomes." (PMID 40761299, 2025). "NHR is a superior index compared to traditional markers like CRP and IL-6, as it combines neutrophil-driven immune activation with HDL-C’s anti-inflammatory effects, providing a more comprehensive view of the adiposity-inflammation-depression axis." (PMID 41162914, 2025).
depression (continued). "Another RCT indicated that engaging in physical activity led to decreases in both the pro-inflammatory marker IL-6 and depressive symptoms in individuals diagnosed with depression, however, CRP levels were not available in this analysis." (PMID 41661985, 2025). "Patients with depression often exhibit increased levels of interleukin-6 (IL-6), IL-1β, IL-10, tumour necrosis factor-α (TNF-α), CRP, and transforming growth factor-β (TGF-β), many of which are produced in response to cellular stress through inflammasome activation." (PMID 41226736, 2025). "For anxiety or depression, individual indices WBC, platelets, neutrophils, CRP, GlyA and composite indices NLR, SII, SIRI, INFLA all showed significant mediating effects, with intermediate ratios of 3.13, 1.85, 4.84, 6.68, 5.86, and 3.52%, 4.55, 4.06, 9.00%, respectively." (PMID 41550866, 2025). "First, it is important to consider that group designations were randomized based on CRP levels; however, we did not recruit in a way that selected those with only inflammation-related depression and/or anxiety." (PMID 41374012, 2025). "Moreover, increased concentrations of blood-derived inflammatory markers, such as C-reactive protein (CRP), have been observed in both depression and anxiety." (PMID 40823322, 2025). "Proposed mechanisms of the development of sleep disturbances include the release of cytokines such as tumor necrosis factor (TNF) or C-reactive protein (CRP), depression and distress, cancer-related fatigue, menopausal hormone therapy (MHT), chemotherapy, radiotherapy, and surgery." (PMID 41357522, 2025). "In clinical populations, IL-6, IL-1β, and CRP were elevated among women with depression, whereas these markers were not elevated in men, and rather men displayed elevated levels of IL-17." (PMID 40305313, 2025). "Given our focus on genetic, state, and trait factors in immune-metabolic functioning, we have greatly simplified the immunologic profile of depression in considering only CRP and do not assume generalizability beyond the innate-immune domain." (PMID 41431700, 2025). "Canonical pro-inflammatory cytokines, such as CRP, IL-1β, IL-6, and TNF-α, influence the central nervous system (CNS) function and contribute to changes in mood, social behavior, emotion regulation, and the onset and prognosis of depressive disorders." (PMID 41333345, 2025). "In recent years, a series of studies have noted that biological indicators in peripheral blood samples, mainly IL-1, IL-6, TNF-α, IFN-α, C-reactive protein, neurotrophic factor and KYN pathway metabolites, can be analysed as criteria for the diagnosis of depression." (PMID 39654767, 2024). "Observations indicate a sustained elevation of CRP levels in stroke survivors up to 18 months post-event, although this elevation does not correlate directly with depression diagnoses." (PMID 38377025, 2024). "In addition, there is a certain correlation between depression and serum inflammatory factors such as IL-6, TNF-α, and CRP." (PMID 38698338, 2024). "Another link between depression, cognitive disorders, and CHF seems to be related to alterations of neurohormone levels such as cortisol or to the presence of pro-inflammatory cytokines (IL-6, TNF-α, C-reactive protein)." (PMID 39597044, 2024). "Besides raised levels of inflammatory cytokines and mediators, the C-reactive protein (CRP), commonly used as inflammatory marker, is increased in different psychiatric disorders, such as depression and schizophrenia." (PMID 38796643, 2024). "Similar numbers of participants had decreases in their FCP, serum CRP, and serum IL-6 in both groups, suggesting that changes in depression scores did not impact measures of IBD activity." (PMID 38839073, 2024). "Therefore, further research in specific populations is necessary to explore the correlation between CRP levels in TBI patients and delirium, anxiety, and depression." (PMID 39554848, 2024).
depression (continued). "Similar to our results, the authors report that patients with T2DM and comorbid depression had elevated levels of CRP and IL-6 compared to those diabetic subjects without depression." (PMID 39409133, 2024). "In line with this notion a negative correlation between C-reactive protein concentration and anterior and mid-corpus callosum volume has been demonstrated in elderly patients with depression." (PMID 38186634, 2024). "A study from Poland found significantly higher levels of both IL-6 and CRP in study participants with depression than in those without." (PMID 38575920, 2024). "Of course, our findings should not be interpreted as saying that serum CRP is not a clinically-relevant biomarker in depression." (PMID 37264010, 2023). "After receiving corticosteroids treatment for one month, CRP levels in IBD patients with anxiety/depression symptoms were considerably higher than those without (p = 0.032)." (PMID 37547213, 2023). "Pearson’s correlations revealed no concurrent correlations between depression and CRP for both 2011 and 2015 (ps > 0.05, ranging 0.07–0.36) studies." (PMID 36860788, 2023). "Specifically, we observed consistent genetic correlations between our female-specific GWASs from the UKB and other both-sex combined GWASs (MVP-UKB depression = 0.81, MVP-UKB anxiety = 0.72, and CHARGE-UKB C-reactive protein [CRP] = 0.99) (eTable 5 in Supplement 1)." (PMID 36652249, 2023). "Another limitation was the lack of proper settings and funding for multiple testing of vitamin D and CRP levels in our patient cohort, as well as the absence of checking these markers in other mental disorders, such as depression or anxiety disorders." (PMID 37803327, 2023). "Of note, pro- and anti-inflammatory cytokines, but not CRP, were inversely correlated with severity and neurological assessments in major depression." (PMID 36983411, 2023). "Studies have primarily assessed whether there is a relationship between the peripheral concentration of pro-inflammatory markers such as c-reactive protein (CRP), interleukin-6 (IL-6) and tumor necrosis factor-α (TNF-α) and the development of depression." (PMID 37928924, 2023). "People who had depression scores of <2 were older, more physically active, more likely to be non-smokers, and had lower CRP levels and higher serum magnesium levels than those with a depression score of ≥2." (PMID 37049401, 2023). "After adjustment for baseline values of appetite, CRP, age, smoking, NIHSS, history of stroke, fatigue, stress, anxiety, and depression, the adjusted mean difference for appetite was 1.38 (95% CI, 0.19 to 2.56) for patients who received RJ compared to those of the placebo group." (PMID 38260068, 2023). "A previous RCT with partially medicated patients with depression and elevated cardiovascular risk did also not observe an effect of CBT on CRP." (PMID 35232509, 2023). "Unipolar depression (Major Depressive Disorder—MDD) has generally been found to stimulate a pro-inflammatory Th1 response (IL-1, IL-2, soluble IL-2 receptor (-sIL-2R), IL-6, C-Reactive Protein (CRP), TNF-α, and IFN-γ), with a subsequent increase in tryptophan catabolites (the kynurenine pathway)." (PMID 37510730, 2023). "Another network analysis found that persons with (v. without) heightened CRP had more notable edges in a depression network, with thicker networks indicating more significant psychopathology (Moriarity, van Borkulo, & Alloy, 2021b)." (PMID 35924730, 2023). "The studies of CRP in depression, therefore, do not all utilize the same definitions of ‘high’, ‘low’, or ‘mid’ CRP levels." (PMID 38250276, 2023). "Although classic inflammatory markers such as CRP, IL-6, and TNF-α are associated with depression and vitamin D deficiency, they do not seem to be all the mediators of this link." (PMID 37049606, 2023).